C1QL1 (complement C1q like 1)
Description:
May regulate the number of excitatory synapses that are formed on hippocampus neurons. Has no effect on inhibitory synapses (By similarity).
Synonyms: C1QRF; CRF; CTRP14; C1QTNF14
Tractability: Antibody: UniProt places it where antibodies can reach, with medium confidence; UniProt predicts a signal peptide or a membrane-spanning region; its Gene Ontology location is reachable by antibodies, with medium confidence.
Gene: Protein-coding gene on chromosome 17 (44,959,693 to 44,968,303, reverse strand). Ensembl gene ENSG00000131094.
Subcellular location: Secreted
Subcellular location (Human Protein Atlas): Vesicles; Cytosol; Predicted to be secreted
Gene Ontology:
Molecular function: protein binding; signaling receptor binding
Biological process: locomotory behavior; maintenance of synapse structure; trans-synaptic signaling, modulating synaptic transmission; regulation of synapse pruning
Cellular component: synapse; synaptic cleft; cerebellar climbing fiber to Purkinje cell synapse; climbing fiber; cytoplasm; extracellular region; presynapse
Genetic constraint (gnomAD): Loss-of-function variants: 15 observed, 13.08 expected, observed/expected ratio (o/e) 1.15, 90% interval 0.76 to 1.72. The upper end of that interval is the gene's LOEUF score, 1.72, which puts it in group 6 of 6, group 1 being the genes least tolerant of losing a copy. Missense variants: 346 observed, 343.88 expected, observed/expected ratio (o/e) 1.01, 90% interval 0.92 to 1.1. Synonymous variants: 172 observed, 153.66 expected, observed/expected ratio (o/e) 1.12, 90% interval 0.99 to 1.27.
Homologues: Orthologues: chimpanzee C1QL1 (99% identical), macaque C1QL1 (99% identical), dog C1QL1 (98% identical), mouse C1ql1 (98% identical), rat C1ql1 (98% identical), pig C1QL1 (98% identical), rabbit C1QL1 (91% identical), guinea pig C1QL1 (78% identical), zebrafish c1ql1 (31% identical). Paralogues in human: C1QL3 (75% identical), C1QL4 (67% identical), C1QL2 (67% identical), COL10A1 (34% identical), COL8A2 (33% identical), C1QTNF2 (32% identical), COL8A1 (31% identical), OTOL1 (30% identical), C1QTNF7 (30% identical), C1QB (29% identical), C1QTNF9 (29% identical), C1QTNF9B (29% identical), and 11 more.
Diseases named in the same sentence as C1QL1 in open-access papers:
C1QL1 is named in the same sentence as 21 diseases in open-access papers, as found by Europe PMC text mining. Sharing a sentence is not in itself a finding about the gene and the disease. The quoted sentences say what the papers report.
glioma (2 papers, 2021 to 2023). A benign or malignant brain and spinal cord tumor that arises from glial cells (astrocytes, oligodendrocytes, ependymal cells). "Genetic analysis revealed two novel tumor-promoting factors that the authors believe are potential key factors in the early progression of human gliomas: Complement component 1 q subcomponent-like 1 (C1QL1) is a synapse-associated protein with little understood function." (PMID 38275375, 2023). "Among top upregulated oncogenic candidates, we functionally validated C1QL1 as a new glioma-promoting factor." (PMID 33390587, 2021). "We further uncovered stage-specific oncogenic cascades, and among the candidate genes we functionally validated C1QL1 as a new glioma-promoting factor." (PMID 33390587, 2021).
astrocytoma (1 paper, 2025). "Comparison of the grade 3 astrocytoma to the matched normal sample, revealed the top three DEGs encoding ECM glycoproteins (NTN1, AEBP1 and SPARC) and ECM-affiliated factors (C1QA, LGALS9 and C1QL1)." (PMID 41366031, 2025).
atherosclerosis (1 paper, 2022). A disease characterized by the build-up of fatty material and calcium deposition in the arterial wall resulting in partial or complete occlusion of the arterial lumen. "Based on these findings, this study aims to explore the underlying molecular mechanisms governing C1QL1 regulation of atherosclerosis." (PMID 36286293, 2022). "Despite this association, the association between C1QL1 and atherosclerosis is unclear." (PMID 36286293, 2022). "The purpose of this study was to investigate the influence of C1QL1 on atherosclerosis as well as the transcriptomic alteration of the aorta." (PMID 36286293, 2022). "Even though the overexpression of C1QL1 elevated the HDL-C levels in plasma, the plaque formation of atherosclerosis did not decrease due partly to a lack of differences in the practical functionality of HDL." (PMID 36286293, 2022).
breast carcinoma (1 paper, 2025). "Our earlier research discovered that C1QL1 was expressed less in breast cancer (BrCa) tissues than in normal breast tissues by analyzing the gene profile of RNA sequences." (PMID 40583061, 2025).
differentiated thyroid carcinoma (1 paper, 2018). Differentiated thyroid carcinoma (DTC), also known as papillary or follicular thyroid carcinoma, is a slow-growing malignancy usually presenting in adults as an asymptomatic thyroid mass. "Gene expression of C1QL1 (a), LCN2 (b), CRABP1 (c) and CILP (d) genes was measured by real-time quantitative PCR in normal thyroid (NT) tissues, follicular thyroid adenoma (FTA) and differentiated thyroid cancer (DTC)." (PMID 29321030, 2018).
lung adenocarcinoma (1 paper, 2022). A carcinoma that arises from the lung and is characterized by the presence of malignant glandular epithelial cells. "Moreover, C1QL1 can specifically bind to the adhesive G-protein-coupled receptor 3 and may participate in synaptic homeostasis, such as synapse formation, maintenance, and elimination, so C1QL1 is used to promote migration and proliferation in lung adenocarcinoma." (PMID 36286293, 2022).
lymphocytic thyroiditis (1 paper, 2018). "Gain of C1QL1 expression was significantly associated with extrathyroidal extension (P = 0.003) and lymphocytic thyroiditis (P = 0.003) in the DTC samples." (PMID 29321030, 2018). "In FTC, gain of C1QL1 expression was present in 71% of wFTC and absent in mFTC (P = 0.007), and lymphocytic thyroiditis was only present in FTC with gain of C1QL1 expression (P = 0.026)." (PMID 29321030, 2018).
Obesity (1 paper, 2022). Accumulation of substantial excess body fat. "Interestingly, a genome-wide association study implicated C1QL1 as a candidate gene associated with total body fat mass, indicating that C1QL1 is a potential new therapy for the aetiology of osteoporosis and obesity." (PMID 36286293, 2022).
thyroid cancer (1 paper, 2018). "Notably, gain of C1QL1 expression was significantly higher in wFTC than in mFTC, reinforcing the assumption that gain of C1QL1 expression is related with thyroid cancer progression." (PMID 29321030, 2018). "Since extrathyroidal extension and tumour size are major prognostic factors of thyroid cancer it may be advance that gain of expression of C1QL1 will probably be a good indicator of clinical evolution." (PMID 29321030, 2018). "Additionally, gain of C1QL1 expression was observed in the larger (> 4 cm) thyroid cancers (OR = 4.60; P = 0.056), thus reinforcing the importance of C1QL1 expression as predictor of thyroid cancer progression." (PMID 29321030, 2018). "Additionally, eight out of ten (80%) thyroid cancer cell lines showed gain of C1QL1 expression." (PMID 29321030, 2018). "Additionally, the use of molecular data for predict the prognostic of thyroid cancer patients remains controversial and the identification of biomarkers with prognostic potential (as we describe here for C1QL1 and LCN2) can further improve the design of this kind of assays." (PMID 29321030, 2018). "A regression model was performed with C1QL1, LCN2, CRABP1 and CILP expression values for thyroid cancer prognostic factors: age of patients (> 45 years), tumour size (> 4 cm), and presence of extrathyroidal extension of the tumour." (PMID 29321030, 2018). "C1QL1 expression levels were successful measured by qPCR in 89 DTC (15 FTC, 20 FVPTC and 54 PTC), 10 thyroid cancer cell lines, 17 FTA, and 18 matched thyroid normal tissues." (PMID 29321030, 2018). "Gene expression values (normalized read counts) of C1QL1 (a), LCN2 (b), CRABP1 (c) and CILP (d) in differentiated thyroid cancer (DTC) and normal thyroid (NT) tissues available in The Cancer Genome Atlas (TCGA)." (PMID 29321030, 2018).
thyroid tumours (1 paper, 2018). "We conclude that the underexpression of CRABP1 and the overexpression of LCN2 may be useful diagnostic biomarkers in thyroid tumours with questionable malignity, and the overexpression of LCN2 and C1QL1 may be useful for prognostic purposes." (PMID 29321030, 2018).
tumor (6 papers, 2018 to 2025). "Taken together, our findings provide fresh insight into the regulatory mechanisms underlying the tumor-suppressive actions of C1QL1 in BrCa." (PMID 40583061, 2025). "In conclusion, our study first identified C1QL1 as a tumor suppressor in BrCa, which was downregulated by promoter hypermethylation." (PMID 40583061, 2025). "The xenograft tumor features and C1QL1 expression were evaluated using IHC, H&E staining and the TUNEL test." (PMID 40583061, 2025). "Decreased PCNA staining and increased apoptotic cells were seen in tumor xenografts of cells expressing C1QL1." (PMID 40583061, 2025). "C1QL1 has been proposed to have a proliferative and tumor-promoting function in 2 different cancers, including one inside the brain, and contributes to the regulation of the ovarian follicle reserve." (PMID 38985832, 2024). "Similarly, the group that overexpressed C1QL1 had smaller average tumor weights in their xenografts." (PMID 40583061, 2025). "In addition, in lung adenocarcinoma, C1QL1 is typically upregulated and facilitates tumor cell growth and invasion." (PMID 40583061, 2025). "In the univariate analysis, gain of the C1QL1 [odds ratio (OR) = 5.34; P = 0.006] and LCN2 (OR = 3.48; P = 0.029) expression were significantly associated with the extrathyroidal extension of the tumour." (PMID 29321030, 2018). "Our results support that C1QL1 can act as a tumor suppressor of BrCa by modulating the C1QL1/HSP90α/VCP-ERS/UPR pathway, implying that the promoter methylation status of C1QL1 or the expression of C1QL1 may represent a potential marker for the diagnosis or prognosis of BrCa." (PMID 40583061, 2025). "C1QL1 interacts with HSP90α and VCP and executes a tumor-suppressive function by enhancing the proteasomal degradation of HSP90α and VCP, consequently leading to ERS/UPR-related caspase-dependent apoptosis." (PMID 40583061, 2025). "In the mRNA group, ZIC5, C12orf75, C1QL1, TMEM74, and GNAZ were significantly upregulated in tumor tissues compared to the adjacent control; PZP and FAM65C were significantly downregulated compared to the adjacent control." (PMID 31156698, 2019). "In PTC, tumours with gain of C1QL1 expression were significantly larger than tumours without C1QL1 overexpression." (PMID 29321030, 2018). "Thus, other forms of cell death, the inhibition of metabolic pathways and the suppression of angiogenesis, which are closely related to the regulation of tumor growth and do not rely on the expression of EMT markers, may also be involved in the C1QL1-mediated growth inhibition of BrCa cells." (PMID 40583061, 2025). "In contrast, we did not observe an upregulation of C1QL1 in HOPX+ embryonic hNSCs during human hippocampal development, which also underwent neurogenic-to-gliogenic switch, suggesting that the upregulation of C1QL1 is tumor-specific and may promote tumorigenesis." (PMID 33390587, 2021).
cancer (3 papers, 2018 to 2025). A tumor composed of atypical neoplastic, often pleomorphic cells that invade other tissues. "They found that increasing C1QL1 levels slowed cancer cell growth and spread by causing cell death through a process called apoptosis." (PMID 40583061, 2025). "Overexpression of C1QL1 inhibits BrCa cell proliferation, metastasis and promotes cancer cell apoptosis both in vitro and in vivo." (PMID 40583061, 2025). "It is probable that C1QL1 regulates different tumors dynamically or that it is determined by diverse interactors in various cancers under varied cellular settings, ultimately contributing to a variety of intracellular activities." (PMID 40583061, 2025). "There are no current reports establishing a possible relation between C1QL1 expression and cancer." (PMID 29321030, 2018).
infection (1 paper, 2022). The state of being infected such as from the introduction of a foreign agent such as serum, vaccine, antigenic substance or organism. "The proinflammatory chemokines CCL3, CXCL3, and CXCL10 were also upregulated following infection, while synapse-related genes, including C1QL1 and SYPL1, were downregulated." (PMID 36314791, 2022).
C1QL1 also shares sentences with these, for which no sentence is quoted: aortic atherosclerosis (1 paper); bacterial infection (1); colorectal cancer (1); deafness (1); glioblastoma (1); lung carcinoma (1); osteoporosis (1); Stroke (1).